C1DP1 (C1D nuclear receptor corepressor pseudogene 1)
Synonyms: bA195O1.1
Gene: Processed pseudogene on chromosome 10 (32,511,336 to 32,511,737, reverse strand). Ensembl gene ENSG00000231245.
Diseases named in the same sentence as C1DP1 in open-access papers:
C1DP1 is named in the same sentence as 1 disease in open-access papers, as found by Europe PMC text mining. Sharing a sentence is not in itself a finding about the gene and the disease.
C1DP1 shares sentences with these, for which no sentence is quoted: melanoma (1 paper).